CD4 (CD4 molecule)
Diseases named in the same sentence as CD4 in open-access papers (continued):
Sharing a sentence is not in itself a finding about the gene and the disease.
diabetes (continued). "In our study, PFK15 treatment led to increased PD-1 and LAG-3 expression on CD4+ T cells that correlated with protection from diabetes onset." (PMID 34163475, 2021). "The percentage (p = 0.010) and number (p = 0.002) of CD4+ TLR2+ T cells in patients with newly diagnosed type 1 diabetes mellitus were higher compared to the control group." (PMID 34830017, 2021). "Our study reported that patients with diabetes present a greatly reduced number of lymphocytes, especially the decreased counts of peripheral CD4+ T cells, CD8+ T cells, and NK cells compared to patients without diabetes in SARS-CoV-2 infections." (PMID 33776910, 2021). "The leading PAFs for ARD were declined estimated glomerular filtration rate (eGFR) (39.68%) and low CD4 count (39.61%), followed by diabetes (10.19%)." (PMID 33620297, 2021). "A recent approach of co-transfer of CD4 + CD49b + LAG3 + Tr1 cells along with diabetic splenocytes showed a significant decrease in diabetes in NOD mice." (PMID 33154424, 2020). "Our larger sample of TW (n = 221) had a lower prevalence of viral suppression and diabetes, lower CD4 counts, and higher prevalence of treated hypertension than CW and CM." (PMID 32687532, 2020). "In next stage, the dual approach of immunometabolism for various immune mediated cells such as CD4 T cells and macrophages further promotes development of therapeutics in diabetes and its complications." (PMID 32913271, 2020). "While transfer of diabetic donor CD8+ cells alone cannot elicit diabetes, a highly variable diabetogenic potential of diabetic donor CD4+ cells has been reported." (PMID 33291571, 2020). "Studies on NOD model showed that CD4+ T-cells respond to a series of β-cell proteins, most prominently proinsulin, included in diabetes." (PMID 32802890, 2020). "We next tested the ability of α4+/CD4+ spleen T-cells to cause diabetes, with a most remarkable outcome: all NOD hosts developed diabetes, as before with very short latency, while NOD.α4-/- recipients were completely protected (p < 0.01)." (PMID 33291571, 2020). "The CD4+ cell counts in the diabetes group were lower than those in the other two groups, while the levels of LDH and hs-CRP were higher." (PMID 33062712, 2020). "IL-7/M25 treatment of recipient mice starting as early as day 2 after cell transfer shortened the lapse of time until diabetes development to day 11.5 ± 1.0 if only diabetogenic CD4+BDC2.5+ T cells were transferred (P < 0.05)." (PMID 31024566, 2019). "The associated risk factors for kidney in this population include black race, older age, hypertension, diabetes, low CD4 T-cell count, and high viral load." (PMID 31430930, 2019). "In contrast, at ~9-10 weeks of age (i.e., shortly before diabetes onset), the percentages of CD4+Foxp3+ cells were significantly lower in NOD mice than B6 controls." (PMID 31281853, 2019). "Recently, we reported that CD8+CD57+ T-cell frequency was significantly higher in patients with pre-diabetes and type 2 diabetes compared to subjects with normal glucose tolerance, though CD4+CD57+ T-cell frequency was not27." (PMID 31501486, 2019). "Co-transfer of 1 x 105 CD4+CD49b+LAG3+ Tr1 cells from vaccine-treated animals with diabetic splenocytes (1 × 106) resulted in a significant decrease in diabetes." (PMID 30863412, 2019). "Further experimental evidences in NOD mice demonstrate that PD-1 deficiency or administration of a monoclonal antibody to PD-1 promote and exacerbate diabetes development with more pronounced CD4+ and CD8+ infiltration within insulitis." (PMID 30650147, 2019). "Peripheral blood immune cell subsets after costimulation modulator show that the quantification of CM CD4 T cells can provide a surrogate immune marker for C-peptide decline after diagnosis of diabetes." (PMID 31011577, 2019).
diabetes (continued). "For example, black race, current smoking, diabetes, HCV-seropositivity, and higher HIV viral load were individually associated with higher levels of IL-18, whereas higher CD4+ count was associated with lower IL-18 levels." (PMID 30606136, 2019). "Taken together, our results demonstrate a population of CD57+CX3CR1+GPR56+ co-expressing predominantly CD4+ TEMRA cells in both blood and SAT of PLWH which appear to be associated with diabetes." (PMID 30941121, 2019). "Of all considered variables, sex, income, CD4+ count/mm3, previous history of UTI, history of catheterization, and diabetes were significantly associated with UTI in the bivariate logistic analysis at a p value ≤ 0.25." (PMID 30881531, 2019). "On multivariable analysis, CD4+ cell count <200 cells/μL, diabetes, and S. aureus nasal carriage were found to be independent predictors of S. aureus peritonitis." (PMID 30991864, 2019). "In MLD-STZ diabetes model we showed that resistance to disease in BALB/C mice depends partially on CD4+CD25+Foxp3+ cells." (PMID 30498495, 2018). "In contrast, diabetes was prevented when CD4+ BDC2.5high CD25− T cells were adoptively transferred into sublethally irradiated NOD.Ifngr2−/− but not wild-type NOD recipients." (PMID 30555479, 2018). "Blood glucose, incidence of diabetes, body weight, pancreatic histopathology, the amounts of CD4+T cell subsets, IL-1β level in serum and pancreatic expressions levels of HMGB1, and NF-κB p65 protein were analyzed." (PMID 30410469, 2018). "The advantages of this model are: (i) that diabetes is induced rapidly, and (ii) disease induction is restricted to CD4+ T cells." (PMID 30555479, 2018). "Data from adoptive CD4 T cell transfer model of diabetes in the NOD mouse model suggest that M1 macrophages are required for beta cell destruction in this setting." (PMID 29259578, 2017). "Strikingly, the transfer of diabetes by CD4+CD25− T-cells was totally ineffective in ICOSL−/− NOD.scid recipients, indicating that ICOS-ICOSL interaction is a prerequisite to the transfer of diabetes by naïve effector CD4+ T-cells from diabetic donors." (PMID 28424681, 2017). "The chances of renal disease increase with risk factors such as infection with hepatitis C, and/or B, hypertension, diabetes mellitus and dyslipidemia, low white blood cell count CD4." (PMID 28754089, 2017). "This is in contrast with immune mechanisms involved in diabetes development in the conventional NOD mouse, in which the highest efficiency of diabetes transfer is observed when both CD4+ and CD8+ T-cells are co-injected into naive NOD recipients." (PMID 28424681, 2017). "After adjustment for age, gender, HCV-genotype, RBV, nadir CD4, diabetes, and decompensated cirrhosis, the only variable independently associated with non-SVR12 was the use of suboptimal DAA (HR 2.52; 95%CI 1.24–5.12 vs optimal DAA)." (PMID 28520749, 2017). "A significant delay was observed in transferring diabetes by CD4+ effector T-cells from 40-week-old control ICOSL+/+ into ICOSL−/− as compared to ICOSL+/+ NOD.scid recipients." (PMID 28424681, 2017). "In an adoptive transfer model of T1D, animals treated with MnP demonstrated delayed diabetes progression, concurrent with reduced CD4+ T cell activation." (PMID 28426686, 2017). "Mice protected from diabetes by BTZ in vivo also displayed increased percentages of Foxp3+CD4+ and IDO1 protein expression in both pLNs and pancreata, and an increased systemic Kyn/Trp ratio." (PMID 28450863, 2017). "On multivariable analysis, HIV (HR 1.84, 95% CI 1.07–3.16, P = 0.03), diabetes, and a baseline CD4 count less than 200 cells/μL were found to be independent predictors of peritonitis." (PMID 28158991, 2017). "Adoptive transfer of regulatory CD4 T cells can halt diabetes pathogenesis in mice through inhibition of IFN-γ production by islet-infiltrating CD4 and CD8 T cells and decreased islet infiltration by CD8 T cells." (PMID 29259578, 2017).
diabetes (continued). "In order to test if inhibiting progression to aerobic glycolysis in CD4+ T cells delayed diabetes incidence, an adoptive transfer model was used." (PMID 28426686, 2017). "B6.g7 mice express the same MHC Class II allele as NOD mice, have predominantly naïve insulin-specific CD4+ T cells in the periphery, and remain diabetes-free even after PD-1 pathway blockade." (PMID 27656680, 2016). "The main risk factors for SBI in our setting include low CD4 count, HIV RNA replication, HCV coinfection, but also a history of cancer and diabetes, comorbid conditions that have been frequent in PLHIV in recent years." (PMID 27050752, 2016). "This was considered promising as IFN-γ production from CD4+ T cells that has been shown to be particularly important in the pathology of diabetes in mice as well as men." (PMID 26783747, 2016). "Older age, intravenous drug use, hepatitis C coinfection, lower baseline eGFR, female gender, lower CD4 count nadir, hypertension, diabetes, and cardiovascular disease (CVD) predicted CKD." (PMID 25826420, 2015). "Older age, intravenous drug use, hepatitis C coinfection, lower baseline eGFR, female gender, lower CD4 count nadir, hypertension, diabetes, and cardiovascular disease predicted CKD." (PMID 25826420, 2015). "While there was no statistical difference in weight (pre-treatment and at test), BMI, CD4 count, smoking history, and family history of diabetes and cardiovascular disease between the three groups, an unintended bias cannot be excluded." (PMID 25617630, 2015). "Age, HIV exposure route, hepatitis C coinfection, gender, nadir CD4 count, hypertension, CVD, and diabetes, have all been previously shown to be associated with CKD, so their inclusion in our score was expected." (PMID 25826420, 2015). "The reduction of diabetes is due to a transient increase of Foxp3+ CD4+Treg cells at one week posttreatment." (PMID 26843788, 2015). "In our study, we found lower amounts of Cxcr1 mRNA in neutrophils and CD4+ lymphocytes isolated from NOD mice as compared to diabetes-resistant mice." (PMID 26230114, 2015). "Older age, intravenous drug use, HCV+ antibody status, lower baseline eGFR, female gender, lower CD4 nadir, hypertension, diabetes and cardiovascular disease predicted CKD and were included in the risk score." (PMID 25394023, 2014). "A phase I/II trial using Tr1 cell clones in patients displaying severe Crohn disease, yielded encouraging results and a dose-escalation trial using autologous ex vivo expanded polyclonal Tregs (CD4+CD25+CD127-/lo) in diabetes patients is currently ongoing." (PMID 25256257, 2014). "Further, CD4+ Type II NKT cells were shown as regulators of diabetes and it was shown that these cells were sufficient in down-regulating diabetes, promoting activity of CD4+ BDC2.5 tg T cells in vivo." (PMID 24586872, 2014). "Low CD4 cell count was associated with IGT and diabetes in patients co-infected with HIV, hepatitis C and hepatitis B virus." (PMID 23607267, 2013). "The prevalence of diabetes was 6.74%, 8.45%, 9.69%, and 12.66% among patients with CD4 counts of ≥ 350, 200–350, 50–200, and < 50/mm3, respectively." (PMID 23394285, 2013). "A recent study has also shown that injection of GM-CSF into prediabetic NOD mice prevents diabetes development by inducing IL-10-producing tolerogenic DCs that sustain the suppressive function of CD4+CD25+ regulatory T cells." (PMID 21716731, 2011). "The reduced thymic output leads to secondary peripheral homeostatic alterations in naïve CD4 T-cells, which closely mimic T-cell alterations observed in an experimental animal model of diabetes mellitus." (PMID 22096637, 2011). "Diabetes is significantly reduced or delayed by increase of regulator CD4+CD25+ T cells or NKT cells." (PMID 21483778, 2011). "Treatment with IL-4 has been shown to maintain Th2 CD4+ T cell responses that inhibit the progression of diabetes." (PMID 20686610, 2010).
diabetes (continued). "Here, we report that CB-SC can correct functional defects of mouse CD4+CD62L+ Tregs, leading to reversal of overt diabetes in an autoimmune-caused diabetic NOD mouse model." (PMID 19156219, 2009). "Intriguingly, when their suppression capability was tested in vivo, only p524-pulsed CD4+CD25+ T cells exhibited suppressive effects on diabetes development in co-transfer models." (PMID 19759824, 2009). "We also examined the ability of polyclonal CD4+CD25+ T cells expanded by anti-CD3 plus IL-2 for inhibition of diabetes transfer." (PMID 19759824, 2009). "The results showed that blockade of IL-10/TGF-β bioactivities in vivo dramatically abrogated the suppressive effects of p524-expanded CD4+CD25+ T cells on adoptively transfer of diabetes." (PMID 19759824, 2009). "The relevance of the regulatory role of CD4+CD25+ T cells has been described in different kinds of experimental diabetes models." (PMID 19754943, 2009). "Using a co-transfer model, we subsequently examined the ability of epitope-expanded CD4+CD25+ T cells to suppress diabetes when co-transferred with diabetogenic T cells (1×107 cells/mouse) into NOD.scid mice." (PMID 19759824, 2009). "When CD4+ cells harvested from the pancreatic LN of disease-free CFA-treated NOD mice were depleted of CD25+ cells, the CD4+ cells lost their ability to prevent diabetes development after transfer into young NOD mice." (PMID 19011680, 2008). "Both CD4 and CD8 T cells present in the inflammatory lesion have the potential to cause β cell loss and both are required for spontaneous diabetes." (PMID 17254331, 2007). "Multivariate logistic regression identified older age and low CD4 count (<200 cells/μL) as significant risk factors for diabetes mellitus, whereas the absence of a family history of diabetes was protective." (PMID 41399597, 2025). "After adjustment for years on ART, HCV genotype, current ART type, TAF use, current HIV-RNA, CD4 count, diabetes, BMI, and age, a significant reduction in CAP changes over time (β = −2.85, 95% CI: −5.07 to −0.64, p = 0.01) was associated with the presence of dyslipidemia." (PMID 40733523, 2025). "To address whether CD4-targeted Bcl6 elimination prevents diabetes even when such a “T1D-poised” B cell repertoire has formed, we generated VH125SD.Bcl6fl/fl.NOD (termed VH125SD.NOD hereafter) and VH125SD Bcl6fl/fl.CreCD4.NOD (termed VH125SDBcl6ΔCD4) mice." (PMID 40909612, 2025). "Among PLWH, CD4+ TEMRA and CD4+ CD28− T cells have also been associated with incident diabetes." (PMID 41194668, 2025). "Similarly, immunocompromising conditions such as HIV and diabetes increase the risk, as indicated by RR values of 2.8 for HIV with CD4 counts less than 200 and 4.4 for diabetes mellitus, respectively." (PMID 40217166, 2025). "Using RIP-OVAhi bone marrow chimeras, we previously reported that HPSE-1 from multiple sources, including activated donor OTII (CD4) T cells, and host cells (e.g., radio-resistant endothelial cells and bone marrow-derived platelets) are required for the optimal induction of diabetes." (PMID 40362360, 2025). "The current results are consistent with empagliflozin modulating levels of inflammatory molecules and may potentially lower inflammation in diabetes by decreasing glucose uptake into CD4+ T cells, resulting in e.g. decreased IFNγ release from the cells." (PMID 40599791, 2025). "After adjusting for baseline AST/ALT levels, baseline CD4+ count, alcohol use, BMI, HIV risk factors, diabetes, age, sex, and HBsAb positivity, pOBI remained unassociated with the risk of transaminase elevation, with minimal changes in the hazard ratio estimates for both cohorts." (PMID 40327718, 2025). "S‐specific CD4+ T cells from the ND group displayed enhanced antigen experience as compared with T1D, with a higher proportion of memory T cells compared with diabetes groups and a lower proportion of naïve T cells (TNAIVE) compared with participants with T1D." (PMID 41367201, 2025).
diabetes (continued). "Considering that 6.9HIP-specific CD4+ T cells have been shown to accumulate in pancreatic islets in NOD mice at advanced stages of diabetes, we hypothesized that levels of 6.9HIP might increase in islets from aged NOD mice." (PMID 38455055, 2024). "CD4+ T cells include Th1 and Th2 cell subsets, and imbalance of Th1/Th2 cell differentiation and their cytokine products are dominant features of islet β cell damage during diabetes mellitus." (PMID 38343632, 2024). "The univariable analysis showed that BMI, hyperlipidemia, diabetes, chronic obstructive pulmonary disease, hypertension, coronary heart disease, Framingham risk score, CD3+, CD4+, CD8+, TC, TG, and miR-28-5p were significantly associated with post-EVAR death in AAA patients (all P < 0.05)." (PMID 38664759, 2024). "Moreover, except for its osteogenic properties, ART can also alleviate the incidence of diabetes through increasing the proportion of IL-4-producing CD4+T lymphocytes (Th2) while reducing IFN-γ-producing T lymphocytes (Th1)." (PMID 38509482, 2024). "The reduction in CD4 central memory cells in NGT obese participants may be protective against the development of diabetes as this specific population is increased in T2D." (PMID 38334487, 2024). "Co-transfer of CD4+ and CD8+ T cells from NOD mice into Rag1−/− NOD mice upregulated the incidence of diabetes, whereas co-transfer of CD4+ and CD8+ T cells from IL-27rα−/− NOD mice into Rag1−/− NOD mice did not induce diabetes, demonstrating that IL-27 signaling is essential for T1D development." (PMID 38566992, 2024). "Alterations CD4+ T cell populations such as these are commonly observed in patients with diabetes." (PMID 38214784, 2024). "In obese patients with diabetes, there may be an elevation of activated CD4, CD278 co-stimulatory T-cells, Th17 cells, and cytotoxic T-cells." (PMID 38699234, 2024). "Furthermore, increased serum levels of granzyme B have been independently associated with T2D diagnosis, underscoring the potential significance of CD4 Tcyt cells in the pathophysiology of diabetes." (PMID 39072276, 2024). "CD4+ T helper cell counts were also decreased in patients with diabetes." (PMID 37109747, 2023). "Our study confirmed that uncontrolled diabetes, platelets < 45 × 109/L, CD4+ T cell < 319/μL and CD8+ T cell < 395/μL could be considered independent predictors for development of IPA." (PMID 36707667, 2023). "Additionally, higher baseline frequencies of CD4+ T effector memory RA+ (TEMRA) cells (CD45RA+ CD27-) and senescent T cells (CD4+ CD28-) have been associated with incident diabetes in PWH." (PMID 37313404, 2023). "The univariate analysis revealed that age (Odds Ratio [OR]: 1.021, 95% Confidence Interval [CI]: 1.01-1.04, P=0.011), diabetes (OR: 3.91, 95%CI:1.37-11.16, P=0.011), and CD4 count (OR: 0.13, 95%CI:0.03-0.54, P=0.005) were significantly associated with the LAM diagnostic results." (PMID 38145052, 2023). "After for confounders (age, diabetes and CD4 count), patients with diabetes exhibited a three-fold probability of LAM-positive (OR: 3.14, 95%CI:1.06-9.29, P=0.039), and patient with increase in CD4 count, the probability of being LAM-positive decrease (OR: 0.197, 95%CI:0.046-0.85, P=0.029)." (PMID 38145052, 2023). "HIV-specific risk factor, and lower CD4 presented almost twice the significantly increased risks for CVD while the synergistic interaction among traditional risk factors, i.e., diabetes mellitus, dyslipidemia and family history steeply increased the risk for CVD among PLHIV by almost 20 times." (PMID 36915099, 2023). "Studies have shown that in the peripheral blood and the adipose tissue of type 2 diabetes mellitus, helper (CD4+) T cells are more easily polarized to pro-inflammatory Th1 cells and Th17 cells, while the polarization of anti-inflammatory Th2 cells is significantly suppressed." (PMID 37893490, 2023).